CDKN2A (cyclin dependent kinase inhibitor 2A)
Diseases named in the same sentence as CDKN2A in open-access papers (continued):
Sharing a sentence is not in itself a finding about the gene and the disease.
breast carcinoma (continued). "Collectively, in local breast cancer cohort, we found CDKN2A also overexpress in breast cancer tissues." (PMID 37857018, 2023). "Although literature on MTAP loss in breast cancer is scarce, MTAP and CDKN2A loss co-occur with concordance in up to 90% of the cases, enabling indirect estimation of MTAP loss." (PMID 36913304, 2023). "This miRNA had anteriorly been described to alter the cell cycle by affecting CCND1 (cyclin D1), CDKN2A, or the induction of the exit from the quiescent state of the mammary cancer stem cells." (PMID 37046799, 2023). "Prognosis analysis revealed poor OS and RFS rates in breast cancer patients with elevated levels of CDKN2A and PDHA1 and low levels of MTF1, DLD, LIPT1, and FDX1." (PMID 36312586, 2022). "RB, along with p14ARF, the CDKN2A gene product, suppresses E2F family transcription factors that promote cell cycle progression from G1 to S phase in breast cancer cells." (PMID 36499727, 2022). "Adjuvant breast cancer chemotherapy results in a remarkable increase in molecular markers of cellular senescence, namely CDKN2a expression in PBTLs." (PMID 35764927, 2022). "ER + breast cancer frequently demonstrates gain of CCND 1 (cyclin D1) and CDK4 and loss of CDKN2A (p16) and CDKN2C (p18)." (PMID 36229710, 2022). "One candidate is TBX2, a key developmental transcription repressor that was identified in a senescence bypass screen in breast cancer, where it was shown to suppress p16INK4A (CDKN2A) expression." (PMID 34819350, 2021). "As inactivation of the INK4a/ARF (or CDKN2A) locus is a common and critical genetic event in the development of human cancer, p14/ARF was deleted in four pairs of breast cancer samples and one pair of lung cancer sample we investigated (data not shown)." (PMID 33504946, 2021). "A case–control study found evidence for an independent association of PC risk with PGVs in six genes: ATM, BRCA1, BRCA2, CDKN2A, MLH1, and TP5316, five of which (excluding CDKN2A) have a clear link to breast cancer risk." (PMID 34127761, 2021). "Focal deletions involving Cdkn2a and Cdkn2b were found at chromosome 5q32 in 2 carcinomas (10%), as had been repeatedly observed in a subset of radiation-induced rat mammary carcinomas." (PMID 34388197, 2021). "This possibility is also supported by frequent lesions in the RB/E2F pathway in breast cancer, including loss of RB1, CDKN1B (encoding p27), and CDKN2A as well as amplification of CCND1." (PMID 32985974, 2020). "The discovery of genetic alterations of CDKN2A as well as other cell cycle regulators in breast cancers has led to the approval of CDK4/6 inhibitors (palbociclib) for the treatment of ER+/HER2‐ advanced/metastatic breast carcinomas." (PMID 32279409, 2020). "In a query of The Cancer Genome Atlas (TCGA) database, we found that PIK3CA was the most frequently mutated gene in breast cancer, while MYC and CDKN2A/B were the genes most frequently associated with amplifications and deletions, respectively." (PMID 32498332, 2020). "While rare, we noticed clinically significant mutations in CDKN2A, which belongs to the cell cycle pathway, in the HER2+ subtype of breast cancer (P < 0.05), indicating the potential benefit of CDK4/6 inhibitors." (PMID 33173047, 2020). "Gain of the CCND1 and CDK4 and loss of the CDKN2A (p16) and CDKN2C (p18) genes are present in patients with luminal B breast cancer and poor prognosis of and negatively regulated by the cell cycle pathway." (PMID 33110086, 2020).
breast carcinoma (continued). "The drug combination inhibited DNMT3a protein levels and increased expression of the tumor suppressor gene Cdkn2a/p16 in mammary tumors of HF offspring." (PMID 31889127, 2019). "Of these, Cdkn2a mRNA expression was downregulated in the mammary tumors of HF offspring, and treatment with VPA/hydralazine reversed this downregulation." (PMID 31889127, 2019). "For instance, we identified Chr9 deletions that encompassed CDKN2A as a robust biomarker for poor prognosis in breast cancer." (PMID 30526857, 2018). "Considering the actionability of specific alterations based on OncoKB, CDKN2A homozygous deletion (level 4 evidence), and both oncogenic mutations in PIK3CA were considered clinically actionable (level 3A evidence for breast cancer)." (PMID 29755676, 2018). "The correlations between mutational status and response to CDK4/6 inhibition are also clear in breast cancer, where downregulation of CDKN2A and amplification of CDK4 or CDK6 were correlated with sensitivity to CDK4/6 inhibition." (PMID 29644000, 2018). "For single-gene loci, hypermethylation of CDKN2A in colorectal cancer, MGMT in glioblastoma, BRCA1 in breast cancer were reported to be associated with poor clinical outcomes." (PMID 30217224, 2018). "Among the eight gene-specific regions investigated, exon 2 of CDKN2A was most frequently methylated in tumors, tumor-adjacent and tumor-distant tissues from breast cancer patients." (PMID 28403857, 2017). "Module 2 includes genes whose abnormal function has been directly associated with breast cancer, such as MAPK14, BRCA1, CDH1, HIF1A, CDKN2A and other members/regulators of the CDK family." (PMID 29093438, 2017). "The gene is located at 9p21, a chromosome region often deleted in breast carcinomas, similar to CDKN2A, a recognized tumor suppressor gene." (PMID 26751376, 2016). "This suggests that, in breast cancer, methylation affects CDKN2A expression, independently of DNA copy number change." (PMID 26860128, 2016). "Here, we characterized gene expression (mRNA and protein levels) of MTAP and CDKN2A in seven breast cancer cell lines and performed a promoter methylation analysis of MTAP." (PMID 26751376, 2016). "Three additional SNPs, including rs1011970 (9p21/CDKN2A/2B), rs941764 (14q32/CCDC88C), and rs17529111 (6q14/FAM46A), showed a significant association in analyses conducted by breast cancer subtype." (PMID 23593120, 2013). "SNPs rs1011970 at 9p21/CDKN2A/2B and rs941764 at 14q32/CCDC88C were associated with ER+ breast cancer with ORs (95% CI) 1.27 (1.05–1.54) (P = 0.014) and 1.26 (1.02–1.56) (P = 0.032), respectively." (PMID 23593120, 2013). "RNO5q32 is homologous to human chromosome 9p21 that among a number of important tumor suppressor genes, harbors the CDKN2A/2B locus with its deletion frequently reported in different cancer types, including breast cancer." (PMID 22894538, 2012). "For example, CDKN2A is hypermethylated across colorectal, lung and breast cancer with an average maximum probability of 0.8 and a total of 306 evidence sentences." (PMID 22168213, 2011). "In human breast cancer specimens, the frequency of entotic structures was increased in tumor regions with low levels of staining for p16INK4a, suggesting, overall, that the expression of tumor suppressor proteins encoded by CDKN2A reduces the frequency of entosis in cancer." (PMID 38565900, 2024). "However, although above results implied CDKN2A is an oncogene in breast cancer, the expression level of CDKN2A is negatively related with drug score (CTX, DTX, PTX, DDP, and TAM)." (PMID 37857018, 2023). "In addition, CDKN2A is a susceptibility gene for head and neck squamous cell carcinoma (HNSCC), lung cancer, esophageal cancer, neural system cancer, breast carcinoma, and sarcomas." (PMID 38201484, 2023). "In fact, CDKN2A overexpressed in 33 of 34 types of cancers, including breast cancer." (PMID 37857018, 2023).
breast carcinoma (continued). "As previous studies reported, CDKN2A-mediated molecular subtypes identified drug sensitivity differences in afatinib, erlotinib, and lapatinib, and the higher expression of CDKN2A implied worse outcomes and molecular subtypes in breast cancer." (PMID 37857018, 2023). "CDKN2A was involved in tumor cell growth and drug resistance in human breast cancer." (PMID 35937995, 2022). "Current studies show that EZH2/NXPH4/CDKN2A axis can participate in regulating the proliferation and migration of non-small-cell lung cancer cells revealing a poor prognosis in the prognosis model of breast cancer." (PMID 36245981, 2022). "Through gain and loss of function and rescue experiments, we confirm that MIR200CHG regulates the expression of tumor-associated proteins CDKN2A, cyclin D1, cyclin E1, BCL2, BAX, MMP1, MMP2, and MRP1 by binding YB-1, thereby promoting breast cancer proliferation, invasion, and resistance." (PMID 34272387, 2021). "In the phase II clinical study PALOMA-1, it was found that patient selection based on CCDN1 amplification and/or P16 loss (CDKN2A deletion) did not improve outcomes of the administration of palbociclib plus letrozole in HR-positive breast cancer patients." (PMID 31652270, 2019). "PAL, a specific CDK 4/6 inhibitor, could cause cell cycle arrest in breast cancer cell lines with functional Rb and high CCND1 expression but low CDKN2A expression." (PMID 30236142, 2018). "Our study helps define the mutational spectrum in breast cancer patients suggestive of LFS, contributes to a potential relevance of CDKN2A/p14ARF in LFS/LFL settings, and points out the need for intensified research on monoallelic variants in Fanconi pathway and RECQ family genes." (PMID 30086788, 2018). "Expression profiling revealed 780 genes for which the expression level was affected by the loss of DIP2C, including the tumour-suppressor encoding CDKN2A gene, the epithelial-mesenchymal transition (EMT) regulator-encoding ZEB1, and CD44 and CD24 that encode breast cancer stem cell markers." (PMID 28716088, 2017). "Since frequent MYC amplification and CDKN2A/B deletions were also seen in a recently established bank of human breast cancer PDXs, these genetic events may contribute to efficient engraftment." (PMID 28430642, 2017). "We analyzed MTAP and CDKN2A gene (RT-qPCR) and protein (western-blotting) expression in seven breast cancer cell lines and evaluated their promoter methylation patterns to better characterize the contribution of these genes to breast cancer." (PMID 26751376, 2016). "In addition, a SNP located in a block encompassing CDKN2A and CDKN2B at 9p21, rs1011970, was reported to be associated with breast cancer in a recent genome-wide scan." (PMID 24915306, 2014). "Examples of other hypermethylated genes used to predict poor clinical prognosis include CDKN2A in colorectal cancer, RASSF1A and APC in breast cancer, the apoptosis-associated gene DAPK1 in lung and head and neck cancers, and CDKN2A, RASSF1A, cadherin 13 (CDH13) and APC in stage I NSCLC." (PMID 25473433, 2014). "According to our results, we could suggest that hypermethylation of CDKN2A is possible event leading to its inactivation in late stage breast cancers." (PMID 24093668, 2013).
breast carcinoma (continued). "We replicated previously reported breast cancer susceptibility alleles in these BRCA2 mutation carriers and for several regions (including FGFR2, MAP3K1, CDKN2A/B, and PTHLH) identified SNPs that have stronger evidence of association than those previously published." (PMID 23544012, 2013). "In addition to estrogen signaling and resistance to therapy, 7 of the identified genes have been previously associated with cell cycle regulation (CCND1, CDKN1A, CDKN1B, and CDKN2A) and breast cancer aggressiveness (CLDN7 and DLC1)." (PMID 22616718, 2012). "As cuproptosis-promoting genes, FDX1, LIAS, LIPT1, DLD, DLAT, and PDHA1 were under-expressed in breast cancer; at the same time, CDKN2A, which inhibited cuproptosis, was over-expressed in breast cancer, suggesting that cuproptosis might involve in the protective mechanism of BRCA." (PMID 39432636, 2024). "Thus, CDKN2A and SLC31A1 may be two most potential genes associated with cuproptosis in breast cancer." (PMID 37884650, 2023). "Furthermore, the methylated exon 2 of CDKN2A gene was considerably excessive when compared with CDKN2A promoter in breast carcinoma, and therefore, could have a connection to breast carcinogenesis." (PMID 33896386, 2021). "Furthermore, variants in other cancer susceptibility genes (i.e., MUTYH and CDKN2A) are sometimes reported through breast cancer risk assessment, but were not assessed in this study." (PMID 32866190, 2020). "Expression of mRNA for COX2, P16/INK4A, and KI67 (encoded by PTGS2, CDKN2A, MKI67, respectively) and estrogen receptor beta (ERβ, encoded by ESR2) were analyzed because prior studies suggested these as biomarkers of AH at greater risk of progression to breast cancer." (PMID 31248446, 2019). "Interestingly, previous studies reported that the methylation status of CDKN2A might correlate with the response to certain chemotherapeutic drugs in breast cancer." (PMID 26862903, 2016). "Public data analysis from breast cancer patients revealed post-radiotherapy upregulation of the β-catenin pathway, with elevated CTNNB1, MYC, and CD44 expression, alongside reduced CDKN2A and CDH1 levels, supporting clinical relevance." (PMID 40657369, 2025). "We also analyzed our own ER+ breast cancer patient cohort (NCT04526587), comparing the expression of CCNE1 and CDKN2A before and following progression on CDK4/6 inhibitor-based treatment." (PMID 39924553, 2025). "This study investigated the methylation statuses of CDKN2A/p16INK4A and RB1 genes in breast cancer patients." (PMID 38716944, 2024). "This prospective study aimed to provide a comprehensive analysis of the methylation status of two pivotal genes, CDKN2A/p16INK4A (cyclin-dependent kinase inhibitor 2A) and RB1 (retinoblastoma transcriptional corepressor 1), in breast cancer patients." (PMID 38716944, 2024). "Another study revealed that SFN-ClF combination suppressed proliferation of breast cancer cells by reactivating TSG and cyclin-dependent kinase inhibitor 2A (CDKN2A)." (PMID 38254735, 2024). "By using R language and multiple online databases on 17 candidate cuproptosis-related genes, CDKN2A and SLC31A1 were found to be increased in breast cancer samples with respect to normal tissues." (PMID 37884650, 2023). "The results showed that only CDKN2A and SLC31A1 were significantly increased in breast cancer samples than those in normal tissues." (PMID 37884650, 2023). "Consistent with the data from R language, starBase showed that expression levels of CDKN2A, SLC31A1, ATP7B, and PDHB were markedly up-regulated in breast cancer with respect to normal samples." (PMID 37884650, 2023).
breast carcinoma (continued). "In canine mammary tumors (CMTs), expression of mi-RNA-141 showed post-transcriptional downregulation of the tumor-suppressor gene family INK4A/CDKN2A." (PMID 37510280, 2023). "Experimental studies have shown that CDKN2A, PSAT1, HMGB1, ELAVL1, and SLC7A11 were up-regulated in TNBC, ASNS and LAMP2 were up-regulated in breast cancer and CAV1 was down-regulated in breast cancer, and HELLS was up-regulated in other tumors." (PMID 36568247, 2022). "CDKN2A inactivation is present in the majority of PC patients, increasing cellular fitness and proliferation, and promotes homotypic CIC formation in breast cancer cells." (PMID 35974300, 2022). "CDKN2A/p16 was considered a critical PRC2 target for proliferation blockage upon PRC2 inhibition in many cancers including nasopharyngeal carcer, breast cancer, leukemia, and ovarian cancer." (PMID 35169119, 2022). "The focal CNAs contained several cancer relevant genes, such as the known breast cancer genes EGF, CDKN2A and BAG1 and some were less established including ZAR1 and BMS1." (PMID 33168853, 2020). "The most common actionable genetic alterations in the breast cancer cohort included: 8 PIK3CA (57%), 8 CDKN2A (57%), 6 FGFR (42%), 3 patients with DNA damage repair alterations (21%), and 4 PTEN (28%)." (PMID 30551737, 2018). "These genes include TP63 for bladder cancer, FGFR2 and MAP3K1 for breast cancer, HNF1B for ovarian cancer, KLK3 for prostate cancer, and CDKN2A for skin cancer." (PMID 26374197, 2015). "Grouped by gene, many of these novel mutations comprised large gains in absolute counts and in percent increase, including MAP3K1 and GATA3 in breast cancer, and NOTCH2 and CDKN2A in lung cancer." (PMID 24970867, 2014). "Applying SigFuge to a cohort of lung SQCC samples, we identified CDKN2A, a tumor suppressor gene known to be highly altered in lung SQCC, and KLK12, a gene recently shown to have differential isoform usage in breast cancer." (PMID 25030904, 2014). "Selective depletion of DNMT1 was reported to reactivate expression of CDKN2A/p16 in HCT116 colon cancer cells and re-expression of CDKN2A/p16 after knockdown of DNMT1 in human lung and breast cancer cells." (PMID 25340937, 2014). "5-AZA-CdR reactivates CDKN2a (p16INK4a) in lung cancer, BRCA1 in breast cancer, and MGMT in glioblastomas." (PMID 23369223, 2013). "In male breast cancer, methylation was very rare in BRCA1, CDKN2A, VHL, ATM and CHFR (< 2%) - indicating that methylation of these genes does not seem to play a prominent role in male breast carcinogenesis." (PMID 22765268, 2012). "Previously, we have shown that Id1/3-PA7 regulates the expression of CDKN1A and CDKN1B in a dose-dependent manner in breast cancer cells MCF-7 and MDA-MB-231, which contain the homozygous deletions of the gene CDKN2A." (PMID 20842131, 2010). "We were also able to identify several genes, such as CDKN2A, PCDHGB6, and WT1 well known to be methylated and transcriptionally silent in breast cancer." (PMID 19250546, 2009). "Methylation panel of CDKN2A/p16INK4A gene in the tumor, non-tumor tissue, and cell-free DNA of breast cancer patients." (PMID 38716944, 2024). "FDX1 (P < 1E‐12), LIAS (P = 2.22E‐16), LIPT1 (P < 1E‐12), DLD (P < 5.46E‐09), DLAT (P = 3.14E‐02), PDHA1 (P = 1.15E‐07), MTF1 (P = 1.07E‐09), and GLS (P = 2.48E‐05) were downregulated in breast cancer, while PDHB (P = 5.04E‐07) and CDKN2A (P = 1.62E‐12) were upregulated." (PMID 39432636, 2024).